H19 (H19 imprinted maternally expressed transcript)
Diseases named in the same sentence as H19 in open-access papers (continued):
Sharing a sentence is not in itself a finding about the gene and the disease.
colon adenoma (1 paper, 2012). An adenoma that arises from the colon. "Indeed, increasing Igf2 levels through LOI (heterozygous deletion of H19) or with a keratin 10 promoter increases the number and size of colon adenomas as well as malignant progression in APCMin/+ mice." (PMID 22952916, 2012).
endometrial disorder (1 paper, 2024). A non-neoplastic or neoplastic disorder that affects the endometrium. "Further investigation into the binding potential of miR-301a-3p with H19 and GAS1 revealed a close association of these genes with endometrial disorders and embryo loss, as per the Comparative Toxicogenomics Database." (PMID 38968269, 2024).
Fibroadenoma (1 paper, 2020). A benign tumor of the breast characterized by the presence of stromal and epithelial elements. "Fibroproliferative lesions showed an H19 fold change level of 6.9 (mean ± 3.07), followed by the fibroadenoma lesions with a higher H19 fold change level of 12.5 (mean ± 4.8)." (PMID 33335214, 2020).
fracture (1 paper, 2018). "To further ascertain whether this differential expression was specifically present in AIS patients, we analyzed ADIPOQ mRNA and H19 expression in muscle tissues obtained from a series of 16 age-matched patients undergoing spinal surgery for thoracic spinal fracture." (PMID 30241458, 2018).
growth retardation (1 paper, 2017). "H19 is a long non-coding RNA and placental H19 misregulation is associated with the imprinting disorder such fetal overgrowth disorder (Beckwith–Wiedemann syndrome) and intrauterine growth retardation (Silver–Russell syndrome)." (PMID 28704412, 2017).
hemangioma (1 paper, 2015). A benign vascular lesion characterized by the formation of capillary-sized or cavernous vascular channels. "Furthermore, Beckwith-Wiedmann Syndrome (BWS), where hemangiomas are considered a supportive finding of the diagnosis—is associated with duplications or a loss of imprinting of the IGF2/H19 locus that leads to IGF2 overproduction." (PMID 26496499, 2015).
hemihyperplasia (1 paper, 2025). "Screening recommendations include monitoring children with isolated hemihyperplasia who present isolated hypermethylation of the H19 gene or paternal uniparental disomy of chromosome 11p15." (PMID 40959375, 2025).
hemorrhage (1 paper, 2019). Loss of blood from the vascular compartment to the exterior or into nonvascular body space as a result of rupture or severance of the blood vessels. "By applying both microarray and qRT‐PCR from two different ICH models, we found that H19 is the most upregulated lncRNA after ICH, which remained significant up to 7 days following hemorrhage." (PMID 31557399, 2019).
hippocampal atrophy (1 paper, 2018). "On the contrary, this hippocampal atrophy could be prevented by H19 knockdown with an increased relative ratio of the ipsilateral hippocampus to the contralateral from 60.4% to 75.8%." (PMID 29795132, 2018).
Hodgkins lymphoma (1 paper, 2021). A heterogeneous group of malignant lymphoid neoplasms of B-cell origin characterized histologically by the presence of Hodgkin and Reed-Sternberg (HRS) cells in the vast majority of cases. "qRT–PCR results showed that H19 is significantly overexpressed in Hodgkin’s lymphoma tissues compared to reactive hyperplasia of lymph nodes." (PMID 34977037, 2021). "More importantly, overexpression of H19 promoted Hodgkin’s lymphoma cell proliferation by regulating Akt expression, while H19 knockout exerted the opposite results." (PMID 34977037, 2021). "Recently, H19 was reported to be involved in the pathogenesis of Hodgkin’s lymphoma via the PI3K/Akt signaling pathway, which provides a novel strategy for this cancer treatment by regulating the expression of H19." (PMID 34977037, 2021).
hyperprolactinemia (1 paper, 2023). Abnormally high level of prolactin in the blood. "H19 expression in epithelial and stromal cells is upregulated by chronic hyperprolactinemia, whereas H19 expression is downregulated by dihydrotestosterone." (PMID 37507391, 2023).
influenza (1 paper, 2023). An acute viral infection of the respiratory tract, occurring in isolated cases, in epidemics, or in pandemics; it is caused by serologically different strains of viruses (influenzaviruses) designated A, B, and C, has a 3-day incubation period, and usually lasts for 3 to 10 days. "Interestingly, the cleavage site pattern of novel H19 was defined as PIKETR↓GLF and was identical to that of the bat influenza strain A (H18N11) isolated in South America." (PMID 38260204, 2023).
Inguinal hernia (1 paper, 2020). Protrusion of the contents of the abdominal cavity through the inguinal canal. "After removal of four genes without corresponding known coding proteins (i.e., SRS, DIH2, ICR1, and H19) from the inguinal hernia-causative gene list, 79 genes were used to explore the I2D database." (PMID 31910207, 2020).
intracerebral hemorrhage (1 paper, 2022). A cerebrovascular disorder characterized by bleeding into one or both cerebral hemispheres including the basal ganglia and the cerebral cortex. "The expression of lncRNA H19 in brain tissues was upregulated after intracerebral hemorrhage (ICH), which could activate NF-κB and enhance inflammatory responses to aggravate brain edema and neurological injury." (PMID 35501920, 2022).
intraepithelial neoplasia (1 paper, 2022). A precancerous neoplastic process that affects the squamous, glandular, or transitional cell epithelium without evidence of invasion. "This provides us with new insights for further exploring the biological mechanisms of lncRNA H19, LINC00895, and lnc-SRGAP2C-16 in the process of chronic non-atrophic gastritis and gastric mucosal low-grade or high-grade intraepithelial neoplasia to GC." (PMID 35571069, 2022).
lung injury (1 paper, 2022). "Wu’s study showed that H19 was significantly expressed in LPS-induced acute lung injury in rats, and overexpression of H19 may be a protective mechanism." (PMID 36188624, 2022).
malignant glioma (1 paper, 2025). A grade III or grade IV glioma arising from the central nervous system. "In malignant gliomas (GBM), lnc-H19 encodes the 256-aa peptide H19-IRP, which promotes myeloid-derived suppressor cells (MDSCs) and TAM infiltration, as well as T cell depletion, essential for forming an immunosuppressive GBM microenvironment." (PMID 41181701, 2025).
melasma (1 paper, 2022). "Microarray analysis of hyperpigmented skin from patients with melasma showed downregulation of the H19 gene which was not seen in the skin of patients not affected by melasma." (PMID 36231404, 2022).
memory impairment (1 paper, 2020). "Increased H19 aggravated the epileptic seizures, memory impairment and mossy fibre sprouting of the epileptic rats." (PMID 32648622, 2020). "In the present study, we further confirmed that H19 aggravated epileptic seizures, memory impairment and mossy fibre sprouting in the epileptic rats." (PMID 32648622, 2020).
Moyamoya disease (1 paper, 2024). Moyamoya disease (MMD) is a rare intracranial arteriopathy involving progressive stenosis of the cerebral vasculature located at the base of the brain causing transient ischemic attacks or strokes. "Next, the expression levels of five key genes were found to correlate with the expression levels of several moyamoya disease-related genes, with H19 positively correlating with ADARB2 (Pearson r = 0.628) and STK3 negatively correlating with ISG15 (Pearson r = − 0.556)." (PMID 38704490, 2024).
multinodular goiter (1 paper, 2022). Nodular goiter characterized by more than one discrete tissue mass. "This suggests that high H19 gene expression may be used in conjunction with other molecular markers as a diagnostic tool in deciding between conservative and/or surgical treatment for multinodular goiter patients in endemic areas, such as the Amazon." (PMID 35594253, 2022).
neuroendocrine tumors (1 paper, 2024). "In addition, overexpression of a lncRNA H19 plasmid activated VGF and PI3K/AKT pathway in the QGP-1 cell line, suggesting a link between lncRNA H19 and an increase in proliferation and metastasis of neuroendocrine tumors." (PMID 38279330, 2024).
oligospermia (1 paper, 2021). Decreased number of spermatozoa in the semen. "Studies have shown that males who suffer from moderate oligospermia and severe oligospermia are associated with increased incidence to altered methylation profile at H19 gene." (PMID 33748817, 2021).
omphalocele (1 paper, 2017). Omphalocele is an embryopathy classified in the group of abdominal celosomias and is characterized by a large hernia of the abdominal wall, centered on the umbilical cord, in which the protruding viscera are protected by a sac. "A well-defined (epi)genotype–phenotype correlation exists for omphalocele in BWS: it is caused by KCNQ1OT1:TSS-DMR loss of methylation in 86% of the cases, by CDKN1C mutation in 7%, and by UPD or H19/IGF2:IG-DMR gain of methylation in <10% of patients." (PMID 29047350, 2017). "We can surmise that alterations of methylation levels at H19/IGF2:IG-DMR and KCNQ1OT1:TSS-DMR are not primarily associated to omphalocele, in our cohort; conversely, sequence variants at KCNQ1OT1:TSS-DMR and CDKN1C could represent susceptibility factors for the onset of isolated omphalocele." (PMID 29047350, 2017).
ovarian dysfunction (1 paper, 2025). The inability of the ovaries to function. "Changes in the methylation levels of imprinted genes H19 and Peg3 may also lead to ovarian dysfunction." (PMID 41465099, 2025).
papilloma (1 paper, 2015). A benign epithelial neoplasm that projects above the surrounding epithelial surface and consists of villous or arborescent outgrowths of fibrovascular stroma. "A number of genes related to cancer stem cells were validated by qRT-PCR, including Cxcl12/Sdf-1, Pdgfra, Lgr5, Lrg1, Pecam1/CD31, H19 and Src2, which were all significantly upregulated in Nanog-papillomas and Nanog-SCCs relative to control papillomas." (PMID 25988972, 2015).
paraganglioma (1 paper, 2009). A benign or malignant neoplasm arising from paraganglia located along the sympathetic or parasympathetic nerves. "The H19-SDHD double knockout included H19 as the postulated SDHD-modifier, but did not lead to the development of paragangliomas even after 29 months." (PMID 19956719, 2009).
peripheral nerve injury (1 paper, 2021). Injury to a peripheral nerve. "LncRNA H19 was upregulated in the injured DRGs and hippocampus neurons following peripheral nerve injury." (PMID 33898422, 2021).
pneumoconiosis (1 paper, 2016). An occupational lung disorder caused by inhalation of dust particles. "However, the associations between genetic variants in H19 and susceptibility of coal workers’ pneumoconiosis (CWP) have been seldom reported." (PMID 27626436, 2016).
Premature ovarian insufficiency (1 paper, 2020). Amenorrhea due to loss of ovarian function before the age of 40. "In the future, H19 may also prove useful as a novel diagnostic biomarker for ovarian reserve and premature ovarian insufficiency, and has the potential to improve our diagnosis of DOR especially in situations where current ovarian reserve testing has proven inadequate." (PMID 32404103, 2020).
Right ventricular hypertrophy (1 paper, 2021). In this case the right ventricle is more muscular than normal, causing a characteristic boot-shaped (coeur-en-sabot) appearance as seen on anterior- posterior chest x-rays. "lncRNA H19 was reported to be upregulated in decompensated right ventricular, further silencing H19 limited pathological right ventricular hypertrophy, fibrosis and capillary rarefaction." (PMID 34692796, 2021).
Sjögren's syndrome (1 paper, 2021). "In addition, H19 expression was lower in Sjögren's syndrome (SS) BMMSCs than SLE BMMSCs (p < 0.05)." (PMID 34130625, 2021).
Sleep apnea (1 paper, 2026). An intermittent cessation of airflow at the mouth and nose during sleep is known as sleep apnea. "This aligns with studies showing fibroblast-enriched lncRNAs (e.g., H19 and MALAT1) regulate fibrosis, but LncRNA-IH is distinct in its hypoxia-dependent induction—linking environmental stress (e.g., sleep apnea-related hypoxia) to fibroblast activation." (PMID 41563538, 2026).
soft tissue sarcoma (1 paper, 2026). A malignant neoplasm arising from muscle tissue, adipose tissue, blood vessels, fibrous tissue, or other supportive tissues excluding the bones. "In the present study, we demonstrate that the lncRNA H19 is differentially expressed across soft tissue sarcoma subtypes and that, in univariate analysis, low levels of H19 are associated with poor survival in soft tissue sarcoma." (PMID 41521159, 2026). "Data from this platform showed that among 31 cancer types, soft tissue sarcomas (n = 262) had the fourth‐highest expression levels of H19." (PMID 41521159, 2026). "To test H19 expression as a prognostic biomarker in soft tissue sarcoma, we used a large cohort of patients and applied RNA in situ hybridization for H19 on TMA slides." (PMID 41521159, 2026). "Next, we sought to determine whether the expression of H19 in soft tissue sarcoma cells might provide a therapeutic target." (PMID 41521159, 2026). "Thus, our study aims to pioneer this area of research by comprehensively evaluating H19 in the development and progression of soft tissue sarcoma." (PMID 41521159, 2026). "The molecular regulatory functions of H19 in soft tissue sarcoma are poorly understood." (PMID 41521159, 2026). "In conclusion, our study provides evidence that H19 expression levels vary between different soft tissue sarcoma subtypes and provides unprecedented experimental evidence that H19 might be a valuable target for RNA‐targeting drugs to tackle H19 in soft tissue sarcomas." (PMID 41521159, 2026). "Long non‐coding RNA (lncRNA) H19 plays a pivotal role in the pathogenesis of different human cancers, but its role in soft tissue sarcoma (STS) has not yet been defined." (PMID 41521159, 2026). "However, when adjusted for traditional prognostic factors such as age and tumor size, H19 did not prevail as an independent prognostic factor in soft tissue sarcoma patients." (PMID 41521159, 2026).
testicular cancer (1 paper, 2021). A primary or metastatic malignant neoplasm that affects the testis. "However, in 2018 Wei and colleagues showed how H19 upregulation could in fact directly promote testicular cancer pathogenesis." (PMID 33767982, 2021).
testicular seminoma (1 paper, 2016). A malignant germ cell tumor arising from the testis. "In their study, 9 of 10 testicular seminomas had hypomethylated IGF2/H19 ICRs (≤33% methylated)." (PMID 27034882, 2016).
thalassemia (1 paper, 2025). An inherited blood disorder characterized by a decreased synthesis of one of the polypeptide chains that form hemoglobin. "Meanwhile, in the hematological system of thalassemia patients, H19 expression levels may be regulated, affecting hemoglobin development and maturation." (PMID 40177354, 2025). "Future research could further explore H19 as a potential target for regulating both thalassemia and gut microbiota balance." (PMID 40177354, 2025).
ulcer (1 paper, 2019). "The serum levels of lncRNA H19, together with miR-204, miR-182 were recently proposed as prospective plasma biomarkers to detect GC and its progression from ulcer caused by H. pylori." (PMID 31003545, 2019).
uterine disorder (1 paper, 2024). A non-neoplastic or neoplastic disorder that affects the uterine corpus or the cervix. "The CTD database shows that H19 and GAS1 are associated with uterine disorders, especially embryo loss." (PMID 38968269, 2024).
viral infection (1 paper, 2021). "Similarly, lncRNA H19 binds to the 5′UTR of the viral genome and, more specifically, to the transcript of the viral gene Spike, which has a pivotal role in viral infection." (PMID 33670580, 2021).
tumor (707 papers, 2000 to 2026). "The lncRNA H19 is frequently dysregulated in cancer and associated with tumor development and progression by influencing diverse molecular pathways encompassing cell proliferation, migration, invasion, apoptosis, and metastasis." (PMID 41521159, 2026). "Cox regression and correlation analyses revealed associations between H19 and other ceRNAs in the network with poor prognosis and clinical parameters such as tumor grade and metastasis." (PMID 40556338, 2025). "Clinically, lncRNAs, such as MALAT1, HOTAIR, and H19, are associated with increased microvessel density, tumor progression, and poor prognosis." (PMID 41020820, 2025). "The dysregulation of specific lncRNAs, including LINC01140, MALAT1, HOTAIR, and H19, is closely linked to tumor progression, poor prognosis, and resistance to treatment." (PMID 40723840, 2025). "The expression level of H19 is associated with tumor cell resistance to chemotherapy, possibly by modulating genes related to drug metabolism and apoptosis." (PMID 39286016, 2024). "Higher levels of H19 expression in tumor tissues among EOC patients were found to be linked with shorter overall survival, indicating its potential as a prognostic marker." (PMID 38166752, 2024). "They evidenced that the downregulation of the lncRNA NKILA and NBAT1 are linked to tumor size, whereas the blood concentration of H19 and SPRY4-IT1 is a good parameter to discriminate between BC patients and controls." (PMID 37958880, 2023). "The L3 subtype showed a worse prognosis, potentially due to the abundance of oncogenic lncRNAs, such as DUXAP8 and H19, associated with tumor progression." (PMID 37670949, 2023). "It has been reported that activated tumor-associated macrophages (TAMs) induced H19 expression and promoted HCC aggressiveness." (PMID 36960964, 2023). "h19 expression is significantly higher in tumor tissues of mice with colitis-associated cancer (CAC), and high expression of h19 is also positively associated with CRC The high expression of H19 was also positively correlated with lymph node metastasis in CRC." (PMID 37234178, 2023). "H19 expression was reduced in HCC tumor tissues compared to the adjacent peritumoral tissues, and lower H19 tumor/peritumoral ratios were associated with intrahepatic tumor metastasis, reduced tumor capsule integrity, and decreased disease-free survival." (PMID 35154157, 2022). "In combination with CAI analysis of the tumor serum marker currently in use, it was found that lncRNA H19 expression level was associated with CAI level, while ROC curve analysis showed that H19 lncRNA was better than CAI as a biomarker." (PMID 35310927, 2022). "Loss of IGF2/H19 imprinting is an early oncogenic event that is detected in tumor-paired adjacent normal tissues." (PMID 36231092, 2022). "According to one study, gefitinib exposure causes NSCLC cells to express more H19, which is transferred to other cells via exosomes produced by the main tumor." (PMID 36362424, 2022). "Although the expression of miR-675 was more predictive of tumor size and grade than lncRNA -H19, the current study found that lncRNA-H19 and miR-675 were significantly associated with tumor size and grade." (PMID 36671388, 2022). "In these tumors, the same abnormality also identified in lymphocytes was present and the level of H19/IGF2:IG DMR methylation was greater in the tumor, suggesting a causative role of the GOM in driving oncogenesis." (PMID 35804856, 2022). "Given the oncogenic roles of H19 and the function of gene variation in regulating tumor growth and prognosis, increasing studies have been performed to explore the possible role of H19 SNPs in cancer susceptibility." (PMID 36588790, 2022). "The H19-derived microRNA-675 (miR-675) has been implicated as both tumor promoter and tumor suppressor and also plays a role in liver inflammation." (PMID 33499244, 2021).